TNF (tumor necrosis factor)
Diseases named in the same sentence as TNF in open-access papers (continued):
Sharing a sentence is not in itself a finding about the gene and the disease.
ulcer (continued). "Despite the presence of ulcers in 43% of the skin biopsies, we did not observe a correlation indicating a detrimental role of Th17 cells, probably due to the presence of other mechanisms or cytokines, such as TNF-α, that could be involved in the tissue damage observed in the cutaneous lesions." (PMID 33192178, 2020). "In this study, the detection rates of a bamboo joint-like appearance and erosions and/or ulcers in the duodenum were influenced by the presence or absence of the administration of 5-ASA and anti-TNFα treatment, respectively." (PMID 26376393, 2015). "Elevated levels of cytokines such as tumor necrosis factor α (TNF-α), interleukin-6 (IL-6), interleukin-8 (IL-8) and transforming growth factor-β1 (TGF-β1) have been found in patients suffering from non-healing leg ulcers as compared to healing ulcers." (PMID 35049629, 2021). "Apparently not in line with previous studies, the slight MMP9 expression in active VKC is consistent with the unchanged TNFα values (a major MMP9 modulator) and might be supported by the absence of superficial corneal involvement or ulcers in this study population." (PMID 26989694, 2016).
dermatitis (182 papers, 2010 to 2026). An inflammatory process affecting the skin. "These cells can release a wide range of inflammatory mediators, including IL-8 when stimulated with cytokines typically associated with dermatitis, such as tumor necrosis factor-alpha (TNFα)." (PMID 40430467, 2025). "TNF-α contributes to early skin inflammation and activates keratinocytes, and thus, causes epidermal hyper-proliferation, and IL-1β amplifies inflammatory response and promotes hyperkeratosis." (PMID 39684888, 2024). "Excessive UV irradiation markedly increases the expression of inflammatory markers such as IL-6, IL-17, and TNF-α in skin epidermal and dermal cells, leading to inflammation and associated skin disorders." (PMID 39469625, 2024). "In conclusion, oxidative stress-induced skin inflammation is associated with the release of cellular inflammatory factors (e.g., IL-2, TNF-α, and COX-2), and the expression of these factors is regulated by NF-κB, MAPK, and JAK/STAT signaling pathways." (PMID 36835162, 2023). "It was suggested that the presence of eosinophils and plasma cells were the pathological features of tumor necrosis factor-α inhibitor-associated dermatitis, but eosinophils and plasma cells can also be seen in PSO." (PMID 35628327, 2022). "TNF-ai accounted for the most cases of eczematous reaction, and these cases have been discussed as tumor necrosis factor-alpha inhibitor-associated dermatitis." (PMID 35628327, 2022). "TNF-α has been implicated in radiation mucositis, enteritis, and dermatitis, and its deficiency in a lung injury model has been shown to prevent symptoms of radiation pneumonitis." (PMID 35004305, 2021). "The combined genetic deletions of Tnf or Tnfr with Sharpincpdm/cpdm mice prevented the skin lesions, indicating that TNF-α-mediated apoptosis plays a critical role in dermatitis in Sharpin-deficient mice." (PMID 32403254, 2020). "Loss of TNF or TNFR1 protects cpdm mice from both dermatitis and systemic inflammation, suggesting TNF signaling is the primary driver of inflammation." (PMID 32671059, 2020). "Our data demonstrate that TNF signaling in cFLIP-deficient keratinocytes is the critical factor for the regulation of skin inflammation via modulated cytokine and chemokine expression and, thus, the attraction of immune cells." (PMID 33238518, 2020). "In vivo, the dermatitis seen in the Sharpin-deficient cpdm strain can be reversed by a compound deletion in Tnf indicating that this inflammation is TNF-driven." (PMID 31457011, 2019). "To compare immunopathological changes in Sharpinfl/flFoxp3Cre with those in classical autoinflammatory disease, we used Sharpinfl/flK5Cre mice in which augmented susceptibility to TNFα-induced keratinocyte cell death underlies dermatitis." (PMID 31462647, 2019). "We also showed that aggravated dermatitis and pruritus in the AD rats were related to the elevated expression of Th1 cytokines, such as TNF-α and IL-1β, which are known to be associated with chronic AD lesions." (PMID 28005965, 2016). "TNF-α inhibitors can reduce skin inflammation caused by EGFRIs." (PMID 35372072, 2022). "Therefore, both IL-17 and TNF signaling pathways are involved in the pathogenesis of skin inflammation caused by EGFRIs." (PMID 35372072, 2022). "They noted upregulation of IL-1α, IL-1RA, TNF-α and IL-1α /IL-1RA ratios, as well as time-dependent increase of IL-1B and observed some differences in the inflammatory mechanisms of incontinence-associated dermatitis, depending on the moisture source." (PMID 36555871, 2022). "Furthermore, TNF-α antagonist treatment alleviated skin inflammation caused by imiquimod application." (PMID 32280718, 2020). "Next, we sought to address whether FADD/caspase-8-dependent apoptosis of Sharpin-deficient keratinocytes induces TNF-dependent skin inflammation in Sharpincpdm/cpdm mice." (PMID 25443631, 2014).
dermatitis (continued). "The importance of TTP in regulating cytokine levels is also illustrated by TTP knock-out mice which develop a complex inflammatory phenotype and display inflammatory arthritis, dermatitis, conjunctivitis and myeloid hyperplasia caused by increased cytokine levels, especially of TNFα." (PMID 20594301, 2010). "It attenuated TNF-α-induced inflammatory responses in HaCaT keratinocytes and alleviated dermatitis symptoms in a DNCB-induced C57BL/6 mouse model." (PMID 42075903, 2026). "High levels of IL-17 can induce the production of other inflammatory cytokines, such as TNF-α and IL-1, thereby exacerbating the skin’s inflammatory response and deepening skin inflammation." (PMID 40362388, 2025). "These genes all contribute to immune response regulation as well as TNF and NF‐κB signaling, and their upregulation contributes to the inflammatory responses seen in dermatitis." (PMID 41416938, 2025). "TPA stimulation significantly increased the expression of pro-inflammatory cytokines, including TNF-α and IL-6, which are well-established mediators of skin inflammation." (PMID 41302132, 2025). "Subcutaneous injection of OVA into the sole of the paw causes skin inflammation, with increased levels of interleukins (IL-1beta, IL6, IL13), cytokines (TNF-alpha), and chemokines (CCL11) in the skin of this region." (PMID 40095628, 2025). "Keratinocytes, the main cells in the epidermis, are crucial for regulating skin inflammation by producing mediators like IL-8 when stimulated by agents like TNFα." (PMID 40430467, 2025). "Infusion of hGMSCs in mice improved skin inflammation by suppressing several pro-inflammatory cytokines related to Th-1 and Th-17, such as IL-1, IL-17A, IL-17F, IL-21 and IL-22, as well as TNF-α and IFN-γ." (PMID 40748586, 2025). "TRAIL drives cell death and dermatitis, inhibition of TRAIL-induced cell death can prevent fatal dermatitis, and TNF inhibition combined with TRAIL inhibition improves the development of dermatitis in autoimmune patients." (PMID 39408763, 2024). "EHMF treatment significantly reduced IL-6, TNF-α, and IL-17 levels in the HaCaT skin photoaging cell model, effectively decreasing skin inflammation." (PMID 39469625, 2024). "Our study demonstrated that HPs effectively modulated the production of IL-1β, IL-6, and TNF-α, resulting in a significant reduction in UV-induced skin inflammation." (PMID 38539828, 2024). "CA-infected mice showed extensive dermatitis, confirmed by strong iNOS, TNF-α, IL-1β, and NF-κB genes or immune expressions." (PMID 38858704, 2024). "To elucidate the underlying molecular mechanism by which RA influences skin inflammation, we examined its effect on IFN-γ/TNF-α-induced Nrf2/HO-1 expression in human epidermal keratinocytes (HEKs)." (PMID 39684446, 2024). "Removal of this factor from KCs results in substantial epidermal cell death and spontaneous dermatitis due to improper TNF detoxification, identifying a novel control mechanism preserving skin integrity." (PMID 38649745, 2024). "Based on these findings, the dermatitis model was established in HaCaT using TNF-α and IFN-γ (TI), and the predicted targets were determined through WB and PCR." (PMID 39861084, 2024). "In the context of skin inflammation, inflammatory cytokines such as TNF-α, IL-17A, and IL-22 induce keratinocytes to produce proinflammatory cytokines, including IL-1β, IL-6, TNF-α, and IL-23, which subsequently influence the liver to increase SAA production." (PMID 39519167, 2024). "BSEC in our present study also showed a similar downward trend of pro-inflammatory markers in the DNCB-induced dermatitis mice, in which increased IL-6 and TNF-α in the DNCB group were suppressed by BSEC." (PMID 39519149, 2024). "In summary, our findings suggest the potential for dermatological applications of S. polyrhiza, and that its anti-dermatitis activity is related to the inhibition of TNF and IL-6 by luteolin and luteolin glycosides." (PMID 37686078, 2023).
dermatitis (continued). "In conclusion, our findings suggest the potential for dermatological applications of S. polyrhiza and suggest that its anti-dermatitis action is related to the inhibition of TNF and IL-6 by luteolin and luteolin glycosides." (PMID 37686078, 2023). "Studies indicate that IL-17 contributes to skin inflammation by increasing keratinocyte production of granulocyte–macrophage colony-stimulating factor (GM-CSF), TNF-α, IL-8, and vascular endothelial growth factor (VEGF)." (PMID 38132113, 2023). "Concerning skin disorders, it is well documented that anti-TNF drugs have a key role in the onset of dermatological symptoms, such as urticaria, erythema, and dermatitis, with a frequency ranging from 10% to 60%." (PMID 36365146, 2022). "The transcription factors further regulate the expression of pro-inflammatory genes, such as IL-6 and TNF-α, which ultimately leads to dermatitis." (PMID 35979232, 2022). "The application of forsythoside A to treat dermatitis was mentioned in previous study, by reducing the serum levels of histamine, TNF-α and IgE." (PMID 35055377, 2022). "Crossing ΔKerOTULIN mice onto a TNFR1-deficient background completely prevented dermatitis, even at old age, and ΔKerOTULIN-TNFR1−/− mice showed significantly reduced IL6, TNF, and IL17 levels in their serum." (PMID 34625556, 2021). "The results of the present study indicated that LOC has anti-inflammatory and antiatopic dermatitis effects via various molecular targets by directly or indirectly acting on signalling pathways stimulated by TNFα/IFNγ." (PMID 34795780, 2021). "In keratinocytes, the CO2-induced suppression of TNFα and IL-6 expression was dependent on the pH of the culture medium, indicating that extracellular pH exerts important effects on skin inflammation." (PMID 33431967, 2021). "Using this approach, we previously demonstrated that the exacerbated imiquimod-induced skin inflammation seen in the Zfp36ΔEP mice was strongly dependent on the capacity of keratinocytes to produce TNF." (PMID 33497366, 2021). "Although the data are limited, most recalcitrant TNF-induced skin disorders can be adequately managed by switching to ustekinumab or an anti-integrin receptor blocker." (PMID 33802483, 2021). "Collectively, the results presented in this report demonstrated that scytonemin inhibits TPA-induced skin inflammation in mice, and this was accompanied by decreased expression of TNF-α, and iNOS in inflammatory skin." (PMID 32512874, 2020). "cFLIP is required for epidermal integrity and skin inflammation silencing via protection from TNF-induced keratinocyte apoptosis." (PMID 33238518, 2020). "Ethanol extracts of Ampelopsis brevipedunculata rhizomes inhibited an AD-like skin inflammation through downregulation of serum IgE levels and expression of TNF-α, interferon (IFN)-γ, IL-4, IL-13, and IL-31 in a BALB/c AD model." (PMID 33335525, 2020). "Regarding skin disorders, it is well known that anti-TNFα drugs play a role in the onset of dermatological manifestations, including urticaria, erythema and dermatitis, with a frequency ranging between 10–60%." (PMID 32344563, 2020). "The role of IL-8, IL-17A and TNFα in skin inflammation has been widely described in previous studies." (PMID 33371334, 2020). "Our data support the idea that TNF-α antagonists attenuate skin inflammation and increase TNFAIP3 expression accompanied by the downregulation of Th1- and Th17-related cytokines and phosphorylated p38 levels." (PMID 32280718, 2020). "Six hours after the last application of FAg, mRNA expression of IFN-γ increased by 163-fold in the AD-like dermatitis as compared with that in control mouse skin, and the expression of TNF-α, IL-12/IL-23, IL-17, and IL-22 also increased." (PMID 30838224, 2019). "Further evaluation of its anti-inflammatory abilities in vivo revealed that OIR3 exhibited therapeutic effects by inhibiting oxazolone-induced skin inflammation via inhibition of TNF-α, IL-1β and IL-6 mRNA expression." (PMID 31775224, 2019).
dermatitis (continued). "The expression levels of the three inflammatory factors IL-6, MCP-1, and TNF-α in the cells were also significantly decreased, indicating that MMPs in jellyfish venom are probably vital factors leading to jellyfish dermatitis." (PMID 30857352, 2019). "Suppression of TNFα-mediated dermatitis led to marked rescue of Foxp3 expression in Treg, indicating that reducing the Foxp3+ T cell population in cpdm mice was a secondary effect with respect to chronic dermatitis." (PMID 31462647, 2019). "It is therefore not surprising that interventions that control both skin tissue and serum TNFα levels have been shown to improve features of TPA-induced dermatitis." (PMID 30140696, 2018). "Consistent with the clinical signs of dermatitis, smaller lesion size, more epithelial hyperplasia and more granulation were found in skin biopsies from mice receiving anti-TNF compared with PBS controls." (PMID 28264025, 2017). "Remarkably, germ-free mice responded highly in key parameters, such as total dermatitis score, ear thickness, TNFα, IL-4, and IL-5." (PMID 28290517, 2017). "We found that the most relevant cytokines for the oxazolone model were IL-1β, TNFα, IL-4, and IL-6, which shared more than 25% of their variation with the variation in ear thickness in all dermatitis induced mice." (PMID 28290517, 2017). "In TPA-induced skin inflammation, TNF-α and IL-1β in the serum were reduced by 70% ethanol extract from Asparagus cochinchinensis." (PMID 28358324, 2017). "IL-1β and TNF are important in this model, since both Il1r1−/− and Tnf−/− mice showed significantly reduced dermatitis." (PMID 27982014, 2016). "TNF-α is a well-known proinflammatory cytokine and is markedly increased in DNCB-associated dermatitis." (PMID 26221169, 2015). "Moreover, anti-TNF-α treatment alleviates dermatitis, and TNF-α contributes to the inflammatory process of skin inflammatory diseases." (PMID 40667480, 2025). "In conclusion, topical administration of Roc in psoriatic mice could reduce dermatitis symptoms and inflammatory cytokines of IL-17, IL-23 & TNF-α, which was comparable to the CsA drug in our experiment." (PMID 38402151, 2024). "Dermatitis caused by DNCB and RID both exhibit similar pathological features (ulceration, dermal thickening, inflammation, follicular dropout, sebaceous gland dropout, etc.)and molecular expressions (increased inflammatory factors IL-6 and TNFα)." (PMID 39519149, 2024). "The expression levels of IL-1β, IL-4, IL-6, and TNF-α in peripheral blood positively correlate with the severity of dermatitis and may contribute to disease recurrence." (PMID 39748922, 2024). "However, LUBAC also has a key role in preventing the development of dermatitis by inhibiting keratinocyte death induced by TNF, TRAIL and CD95L." (PMID 39145956, 2024). "Therapies that target TNF-α are conspicuously used in the treatment of different skin disorders, aiming to modulate the in vivo immune functions triggered by many cutaneous cells, including keratinocytes, mast cells, or Langerhans cells, and reduce inflammation taking place within the skin." (PMID 39063004, 2024). "Thus, AP-1 transcription and production of cytokines (e.g., IL-33, TNF-α, IL-4, IL-5, IL-13, and IL-31) were inhibited by curcumin, thereby reducing skin inflammation in psoriatic and AD mice." (PMID 36835162, 2023). "FC alleviated AD apparent symptoms, such as dermatitis score, transepidermal water loss, epidermal thickness, and mast cell infiltration upon declining pro-inflammatory cytokines and mediators, IL-6, IL-5, IL-13, TSLP, and TNF-α." (PMID 37689763, 2023). "Super Protein Multifunction (SPM) was investigated as a potential treatment for managing skin inflammation by monitoring the expression of pro-inflammatory cytokines induced using LPS and poly(I:C)/TNFα in HaCaT keratinocytes and Hs27 fibroblasts as measured via RT-PCR." (PMID 37629159, 2023). "MC-derived TNF was crucial for contact hypersensitivity-induced skin inflammation." (PMID 35807237, 2022).